MTCO2P12 (MT-CO2 pseudogene 12)
Synonyms: COII; COX2; COXII; MT-CO2; MTCO2
Gene: Unprocessed pseudogene on chromosome 1 (632,757 to 633,438, forward strand). Ensembl gene ENSG00000229344.
Diseases named in the same sentence as MTCO2P12 in open-access papers:
MTCO2P12 is named in the same sentence as 10 diseases in open-access papers, as found by Europe PMC text mining. Sharing a sentence is not in itself a finding about the gene and the disease.
MTCO2P12 shares sentences with these, for which no sentence is quoted: mood disorder (2 papers); autoimmune disease (1); breast carcinoma (1); CODAS syndrome (1); colorectal cancer (1); diabetes (1); gastric cancer (1); infection (1); Leigh syndrome (1); tumor (1).